CFTR (CF transmembrane conductance regulator)
Diseases named in the same sentence as CFTR in open-access papers (continued):
Sharing a sentence is not in itself a finding about the gene and the disease.
diabetes (continued). "Most of the interest in CFTR modulator therapy in CFRD has focused on potential benefit, including whether it might prevent or delay onset of diabetes if started early enough in life, improve insulin secretion, and/or reduce CFRD-associated mortality." (PMID 34926166, 2021). "The distribution of ΔF508 CFTR-genotype, treatment with ursodeoxycholic acid, and the presence of diabetes mellitus did not vary significantly." (PMID 22848732, 2012). "The direct effect of CFTR modulator therapies on pancreatic function in patients without preexisting diabetes remains unclear." (PMID 38161769, 2023). "However, not all patients bearing identical CFTR mutations will develop CFRD and variation in diabetes onset as well as disease severity among CF patients with the same mutation suggest that additional factors contribute to CFRD." (PMID 34394004, 2021). "However, the exact molecular background for the development of diabetes is not fully elucidated in CF, partly due to the controversial role of CFTR on beta cells." (PMID 34566890, 2021).
Azoospermia (58 papers, 2011 to 2026). Absence of any measurable level of sperm,whereby spermatozoa cannot be observed even after centrifugation of the semen pellet. "Current recommendations include CFTR mutation screening and genetic counselling for all men with obstructive azoospermia prior to ART, with preimplantation genetic testing (PGT) when both partners are carriers of pathogenic variants." (PMID 41465244, 2025). "The combined results of physical examination (even with doubtful palpable vas deferens), semen analysis (azoospermia, low pH, and low volume), and genetics (two variants in CFTR) can firmly establish the diagnosis of CFTR‐related CBAVD." (PMID 39180390, 2025). "In nine patients (3.1% of total; 13.4% of abnormal) only one (likely) pathogenic variant associated with CF was detected in CFTR, indicating carriership of CF; the subjects with azoospermia had normal volume and/or pH, arguing against a possible missed CBAVD." (PMID 39180390, 2025). "Mutations linked to the CFTR gene were more frequent, with clinical features ranging from azoospermia to oligozoospermia, highlighting the complexity and heterogeneity of presentation." (PMID 39124666, 2024). "The high frequency of the CFTR gene variants in patients with CBAVD/obstructive azoospermia should be taken into account; therefore, their children are at increased risk for both CF and CF-RD patients." (PMID 38003474, 2023). "Three nearby SNPs (rs1515442), (rs1515441), and (rs16846616) in SPATA16 were shown to have a 4~9.6-fold higher mutation incidence in azoospermia compared to oligozoospermia, while CFTR was only 1.8-fold higher." (PMID 37895049, 2023). "The patients with two CF-causing variants in the CFTR gene, including those with the L138ins variant in their genotype, have obstructive azoospermia due to CBAVD syndrome." (PMID 37510311, 2023). "Based on our findings, we establish a strong association between mutations in the CFTR gene, specifically the rs213950 mutation, and the occurrence of oligospermia and azoospermia in this cohort of Taiwanese patients." (PMID 37895049, 2023). "This study reported novel compound heterozygous CFTR mutations (NM:000492.4, Intron: 5T; c.3965_3969dupTTGGG: p.R1325Gfs*5) in two brothers with obstructive azoospermia." (PMID 37489040, 2023). "In mice, impaired expression of Slc9a3 (a Na/H exchanger), reduces the levels of CFTR and causes obstructive azoospermia." (PMID 35725394, 2022). "The majority of the 69 non‐vasectomized men with azoospermia carrying CFTR mutations were Danish; only 11 (15.9%) of the men were of other nationalities." (PMID 33095972, 2021). "All men with azoospermia and suggested compound heterozygosity for CFTR mutations in this cohort were of Danish ethnicity." (PMID 33095972, 2021). "In this study including 639 consecutive men with azoospermia, one or two CFTR mutations/variants were detected in 69 (10.8%)." (PMID 33095972, 2021). "Many studies have documented an extremely high prevalence of CFTR mutations in men with obstructive azoospermia (OA) and CBAVD." (PMID 33095972, 2021). "Semen analyses, hormonal analyses, cytogenetic tests, and Y microdeletion tests are routinely performed in patients with primary infertility, and CFTR gene mutation tests are performed if obstructive azoospermia is suspected." (PMID 34212559, 2021). "In this regard, genetic diagnostic testing for azoospermia is usually based on the detection of karyotype aberrations, Y chromosome microdeletions, and cystic fibrosis transmembrane conductance regulator (CFTR) mutations." (PMID 31973052, 2020). "Our previous research showed that SLC9A3 deficiency causes obstructive azoospermia, degrades the epithelium of the reproductive tract, and drastically suppresses CFTR expression." (PMID 30956978, 2019). "In the same study, further meta-analysis has confirmed the results, showing that the CFTR mutation is associated with azoospermia." (PMID 27483469, 2016).
Azoospermia (continued). "Isolated congenital bilateral absence of vas deferens (iCBAVD) in men results in obstructive azoospermia and is mainly caused by pathogenic variants in cystic fibrosis transmembrane conductance regulator (CFTR) or adhesion G protein‐coupled receptor G2 (ADGRG2)." (PMID 37489040, 2023). "The pathogenesis of azoospermia in males with mutated CFTR genes might be explained by a mechanism that involves the cAMP-response element binding protein (CREB) pathway." (PMID 35725394, 2022). "Among the 639 men with azoospermia, 69 (10.8%) had at least one CFTR mutation." (PMID 33095972, 2021). "Furthermore, also EDNRA and TGF‐β1 gene polymorphisms seem to affect the incidence of CBAVD as well as development of the kidneys, seminal vesicles, epididymides, and ejaculatory ducts in men with azoospermia carrying CFTR mutations." (PMID 33095972, 2021). "It is a great question whether the azoospermia can be explained by other factors than the CFTR mutation in CFTR carriers with present Vasa deferentia." (PMID 33095972, 2021). "Thus, the present cohort is unique since all men with azoospermia were tested for the clinically most relevant CFTR mutations, in addition to careful clinical examination, including palpation of the scrotal parts of the Vasa deferentia." (PMID 33095972, 2021). "Conversely, the histological analysis of a case of obstructive azoospermia (OA), associated with cystic fibrosis transmembrane conductance regulator (CFTR) gene mutation, showed a condition of normal spermatogenesis, with sperm cells at different stages of maturation in the seminiferous tubules." (PMID 34471128, 2021). "One explanation for the higher prevalence of CFTR mutations/variants in non‐CBAVD men with azoospermia might be that the genital tract is obstructed in locations other than the scrotal parts of the Vasa deferentia." (PMID 33095972, 2021). "A significant strength in this study is that clinical examination of the presence of the scrotal parts of the Vasa deferentia as well as examination of the CFTR mutation status was performed in all patients with azoospermia and that all patients were examined by an experienced andrologist (JF)." (PMID 33095972, 2021). "In addition, analysis of the CFTR gene is routinely performed in men with obstructive azoospermia and mutations in the ADGRG2 gene have been recently described to cause a similar phenotype." (PMID 29527098, 2018). "Those three heterozygotes for the Finnish founder mutation for CLD, c.949_951delGTG (p.Val318del), had severe OAT and, in one of the subjects, azoospermia to which an additional contributor may be the heterozygosity of the CFTR 5 T allele." (PMID 29079751, 2017). "Our series with three heterozygotes for the c.949_951delGTG (p.Val318del) mutation revealed severe OAT and, in one of the subjects, azoospermia to which an additional contributor may be the heterozygosity of the CFTR 5 T allele." (PMID 29079751, 2017). "European studies have shown that azoospermia patients have significantly higher 5T mutations compared with oligospermia patients, suggesting CFTR mutations could be related to defective spermatogenesis in humans." (PMID 27483469, 2016). "In this regard, the rapid development of drug targetingCFTR may provide opportunity for the possible therapy of azoospermia caused byfunctional deficiency of CFTR in the testis." (PMID 21625623, 2011). "In fact, the CFTR-dependent sAC-activated cAMPpathway may be an important loop in the FSH-regulated cAMP cascade forspermatogenesis since mutation or abnormal expression of CFTR could result inimpaired spermatogenesis or azoospermia." (PMID 21625623, 2011). "This case expands the intricate genetic spectrum of azoospermia by illustrating the critical role of DDX3Y in the AZFa region in spermatogenesis and the variable penetrance of CFTR variant (TG12-5T) in CBAVD." (PMID 40169970, 2025).
Azoospermia (continued). "Current guidelines indicate that patients with extreme oligozoospermia or azoospermia should be tested for chromosomal imbalances, azoospermia factor (AZF) deletions and/or CFTR variants." (PMID 39180390, 2025). "The diagnostic yield of CFTR and ADGRG2 analysis is around 2 % considering all cases with azoospermia." (PMID 39253719, 2024). "Building upon previous studies, we noted the critical roles of SPATA16 in globozoospermia and CFTR in obstructive oligozoospermia or azoospermia." (PMID 37895049, 2023). "To improve our understanding of cryptorchidism-induced azoospermia, we interpreted testicular GeneChip and RNA-Seq expression data on genes involved in regulating CFTR expression." (PMID 35725394, 2022). "Men with azoospermia and oligozoospermia have deletions on the long arm of the Y chromosome and mutations in the CFTR gene (cystic fibrosis transmembrane conductance regulator)." (PMID 35388312, 2022). "Patients with oligozoospermia, <5 million sperm/ml (EU/USA), or azoospermia are generally offered karyotyping and Y-chromosome microdeletion analysis, while CFTR testing is recommended for men with suspected congenital bilateral absence of the vas deferens." (PMID 34498060, 2021). "Lastly, the following question arises; does it really make sense to restrict the genetic evaluation of azoospermia to karyotyping, CFTR testing and screening for chromosome Y microdeletions?" (PMID 31024732, 2019). "Gene sequencing is currently only performed in very rare cases of hypogonadotropic hypogonadism and the CFTR gene is routinely analysed in men with obstructive azoospermia." (PMID 29527098, 2018). "Our data indicated reduced CFTR levels and obstructed azoospermia-like phenotypes in the reproductive ducts of Slc9a3-/- mice." (PMID 28384194, 2017). "We suggest that the obstructed azoospermia-like phenotypes in Slc9a3-/- mice were attributable to both SLC9A3 deficiency and reduced CFTR expression." (PMID 28384194, 2017). "The pregnancy was achieved by assisted reproduction technology (ART) because of azoospermia of the father with proven compound heterozygosity for p.F508del and p.R117H in the CFTR gene." (PMID 26969265, 2016). "CFTR gene mutations remain the most frequent monogenic origin of obstructive azoospermia, leading to congenital bilateral absence of the vas deferens (CBAVD)." (PMID 41465244, 2025). "Obstructive azoospermia commonly is caused by CBAVD(Congenital Bilateral Aplasia of the Vas Deferens), mainly due to the cystic fibrosis transmembrane conductance regulator (CFTR) and adhesion G protein-coupled receptor G2(ADGRG2) mutations." (PMID 39402445, 2024). "We compared the fertilization rate, 2PN rate, pregnancy rate, miscarriage rate, and live birth rate of CBAVD patients with CFTR gene mutations to non-CBAVD obstructive azoospermia patients from the same period." (PMID 39402445, 2024). "The most frequently seen correlation of CFTR gene mutations is with the congenital absence of vas deferens, which results in obstructive azoospermia." (PMID 39830005, 2024). "In contrast, some studies did not observe an increase in the frequency of the CFTR mutations in men with non-obstructive azoospermia or oligoasthenoteratozoospermia." (PMID 35646184, 2022). "Human genetic studies have shown that point mutations in the CFTR gene were associated with non-obstructive azoospermia and impaired spermatogenesis." (PMID 35725394, 2022). "In this study, only three men with azoospermia (~0.5%) were diagnosed with CBAVD or CUAVD without detection of a CFTR mutation." (PMID 33095972, 2021). "The second aim was to clarify if analysis for CFTR mutations should be performed in men with non‐obstructive azoospermia (NOA) and OA without CBAVD/CUAVD." (PMID 33095972, 2021). "The 18 men with normal testicular tissue had aetiologies characteristic of obstructive azoospermia (OA): 11 had Congenital Bilateral Absence of Vas deferens (CBAVD) based on a CFTR mutation or a history of epididymitis." (PMID 30565706, 2019).
Azoospermia (continued). "Additionally, Slc9a3−/− mice present obstructed azoospermia-like phenotypes possibly attributable to lower CFTR expression, as observed in Cftr-knockout mice." (PMID 30956978, 2019). "Some studies showed significant association between CFTR mutations and non-obstructive azoospermia while the other investigations ruled out this association." (PMID 28042420, 2017). "In clinical studies, loss of CFTR resulted in CBAVD and obstructive azoospermia." (PMID 29286340, 2017). "We undertook the first study of association between CFTR gene mutations and non-obstructive azoospermia in Iran." (PMID 28042420, 2017). "There are just a few studies reporting the association between CFTR mutations and non-obstrucive azoospermia, especially in the Iran." (PMID 28042420, 2017). "We found that Slc9a3-/- mice displayed obstructed azoospermia-like phenotypes, which may be partially contributed to by decreased CFTR expression, similar to that observed in knockout (cf/cf) Cftr mice." (PMID 28384194, 2017). "Evidence from clinical studies has shown increased mutation frequency or reduced CFTR expression in men with congenital bilateral absence of vas deferens or sperm abnormalities, such as azoospermia teratozoospermia and oligoasthenospermia." (PMID 29263816, 2016). "Therefore, the current findings call for moreclinical studies of CFTR mutations screening, both classic genetic mutations andother variant tracts such as IVS8-Tn locus, in azoospermia and severeoligozoospermia patients." (PMID 21625623, 2011). "The present studyreveals a previously undefined role of CFTR and sAC in regulating the cAMP-CREBsignaling pathway in Sertoli cells, defect of which may result in impairedspermatogenesis and azoospermia." (PMID 21625623, 2011). "Decreased CFTR and CREBexpression are also observed in human testes with azoospermia." (PMID 21625623, 2011). "Importantly, CFTR mutations do not appear to contribute to non-obstructive azoospermia (NOA) or primary testicular failure." (PMID 41009940, 2025). "A higher frequency of CFTR mutations is established in cases of non-obstructive azoospermia and oligozoospermia, suggesting the involvement of the CFTR protein in spermatogenesis or sperm maturation, in addition to its role in the development of the epididymis and vas deferens." (PMID 40724872, 2025). "Importantly, endocrine evaluation (hormone levels: FSH, LH, testosterone) and scrotal/transrectal ultrasonography are advised prior to CFTR genetic testing, to verify obstructive azoospermia and rule out other causes." (PMID 41009940, 2025). "The prevalence of azoospermia was significantly higher in patients with 47, XXY karyotype (19, 100%) than in the groups with other chromosomal abnormalities (3, 42.9%; p < 0.001), CFTR gene mutations (17, 73.9%; p = 0.02), and Y microdeletion (10, 71.4%; p = 0.02)." (PMID 39124666, 2024). "Male patients do not suffer from azoospermia, as with other pathogenic variants in the CFTR gene." (PMID 39457459, 2024). "Notably, our findings provide further support for mutations in SPATA16 and CFTR genes being associated with non-obstructive oligozoospermia and azoospermia with normal morphology." (PMID 37895049, 2023). "Interestingly, though, CF was relatively rare in the Chinese population, the CFTR gene variants were not as rare as once believed in obstructive azoospermia based on congenital bilateral or unilateral absence of vas deferens in the Chinese population." (PMID 37489040, 2023). "Consistent with this, some studies have shown that CFTR pathogenic variants may also cause other non-CBAVD Azoospermia, in addition, phenotypic heterogeneity of CF patients with N1303K variant could be explained by the presence of specific haplotypes." (PMID 34190021, 2022).
Azoospermia (continued). "As it is unclear if CFTR mutations may also decrease fertility by mechanisms other than genital tract obstruction, the first aim of this study was to estimate the prevalence of CBAVD in men with azoospermia carrying one or two CFTR mutations." (PMID 33095972, 2021). "Therefore, the deletion of CFTR could also lead to azoospermia through the MSY2 mediated pathway." (PMID 27483469, 2016). "Mutations in the cystic fibrosis transmembrane conductance regulator (CFTR) gene are classically associated with congenital bilateral absence of the vas deferens (CBAVD), causing obstructive azoospermia in an otherwise hormonally normal male." (PMID 41517646, 2026). "In this study, we identified an approximately 384.9 kb AZFa microdeletion in an azoospermia-affected patient, which specifically affects USP9Y without involving DDX3Y, alongside a homozygous CFTR variant." (PMID 40169970, 2025). "Initially, we performed a comparative analysis of the ICSI outcomes between 30 cycles of CBAVD patients with CFTR gene mutations and 112 cycles of non-CBAVD obstructive azoospermia patients." (PMID 39402445, 2024). "Most of obstructive azoospermia patients who carry CBAVD and CFTR gene variants exhibit no symptoms related to CF in China, which is defined as isolated CBAVD (iCBAVD; Cai & Li, 2022)." (PMID 37489040, 2023). "The presence of mutations that do not completely impair the expression of the CFTR gene causes CBAVD in men, with consequent obstructive azoospermia." (PMID 32293822, 2020). "Further studies with greater number of CFTR mutations and patients are therefore needed to examine the role of CFTR in non-obstructive azoospermia." (PMID 28042420, 2017). "Distribution of CFTR and IVS8polyT genotypes in the two groups of patients divided according to the histopathological results: obstructive azoospermia and nonobstructive azoospermia/oligozoospermia." (PMID 25386751, 2014). "Additional targeted molecular tests were applied based on clinical indication: Y chromosome microdeletion analysis in azoospermia or oligospermia, CFTR sequencing in suspected congenital bilateral absence of the vas deferens, and F2/F5 genotyping in recurrent pregnancy loss (RPL)." (PMID 41897629, 2026). "However, the 2PN formation rate in the CBAVD group with CFTR gene mutations was 79.52% (233/293), significantly lower than 86.15% (970/1126) in the non-CBAVD obstructive azoospermia group, with a P-value of 0.0065." (PMID 39402445, 2024). "Toconfirm this pathway in human spermatogenesis and test whether abnormality ofthis pathway may contribute to pathogenesis of azoospermia,we compared theexpression profile of CFTR, CREB and the spermatogenic marker protamine-2 innormal human and non-obstructive azoospermia (NOA) testes." (PMID 21625623, 2011).